NLRP3 (NLR family pyrin domain containing 3)
Diseases named in the same sentence as NLRP3 in open-access papers (continued):
Sharing a sentence is not in itself a finding about the gene and the disease.
Insulin resistance (continued). "Then, to further explore the underlying mechanism by which NLRP3 inflammasome activation affects insulin resistance, we detected the expression and distribution of the IR-AKT-AS160 insulin signaling pathway-related proteins in NTg, NTg + CY-09, 3×Tg-AD, and 3×Tg-AD + CY-09 mice." (PMID 36978970, 2023). "Additionally, the elevated expressions of the NLRP3 inflammasome, IL-1β, and IL-18 in adipose tissues are directly associated with insulin resistance and severity of diabetes." (PMID 36187801, 2022). "Here, we located the main components of the NLRP3 complex in skeletal muscle, and concluded that the activation of this inflammasome is linked to increments in circulating and skeletal-muscle-associated IL-1β during insulin resistance." (PMID 34638553, 2021). "Thus, deletion of the NLRP3 inflammasome enhances healthspan and protects against insulin resistance, bone loss, reduced cognitive function and motor performance." (PMID 34831246, 2021). "Therefore, this shows that hyperglycemia is a strong inducer of NLRP3, and secretion of IL-1β is closely associated with insulin resistance." (PMID 31174550, 2019). "In addition, it was observed that mice deficient in NLRP3 and caspase-1, and fed a high-fat diet, are more protected against insulin resistance." (PMID 28319103, 2017). "Protection from insulin resistance and inflammation following loss of functional NLRP3 may be due to a shift in macrophage polarization, since NLRP3-knockout mice have decreased M1 and increased M2 gene expression profiles in AT." (PMID 26779183, 2015). "It is presently unclear whether persistent Nlrp3 inflammasome activation causes the transition from insulin-resistance to islet decompensation and development of overt T2D." (PMID 23483669, 2013). "Besides, NLRP3 activation caused phenotypic transition in high glucose treated VSMCs while as inhibition of NLRP3 ameliorates VC and insulin resistance in β-cells of rats fed on high fat/glucose diet, also reduced plaque size in ApoE-/- mice fed on high-fat diet." (PMID 41335598, 2025). "In a study conducted on elderly individuals with prediabetes, the impacts of combined Yijinjing and resistance training were investigated to determine whether a direct correlation between the NLRP3 inflammasome and symptoms associated to insulin resistance and liver damage exist." (PMID 40761804, 2025). "Therefore, the causal link between NLRP3, liver pathology and insulin resistance is complex." (PMID 36817440, 2023). "In addition, NLRP3 is associated with insulin resistance and the development of NASH." (PMID 33692776, 2020). "However, a series of findings have shown that statins could promote insulin resistance by activating the NLRP3 inflammasome, which is associated with an increased risk of new onset diabetes." (PMID 29207644, 2017). "A major inflammatory process connecting high SUA levels to insulin resistance is the activation of the NLR Family Pyrin Domain Containing 3 (NLRP3) inflammasome." (PMID 41521685, 2026). "Our previous study revealed that high UA levels regulate hepatic steatosis and insulin resistance through an NLRP3 inflammasome-dependent mechanism." (PMID 40398602, 2025). "Recent studies have demonstrated that activation of NLRP3 inflammasome contributes to insulin resistance and β-cell death in T2D." (PMID 40216765, 2025). "Its documented suppression of the TLR4/NF-κB and NLRP3/caspase-1 axes directly counteracts the chronic low-grade inflammation that underpins insulin resistance." (PMID 41459066, 2025). "It is important to focus on comprehending the significance of NLRP3 inflammasome activation and how it interacts with insulin resistance and oxidative stress." (PMID 39501954, 2025). "It promotes the development of insulin resistance and metabolic syndrome by activating the NLRP3 inflammasome and NF-κB signaling pathways." (PMID 40661082, 2025).
Insulin resistance (continued). "Among these, palmitic acid has been shown to promote mitochondrial ROS production and lysosomal destabilization, both of which contribute to NLRP3 activation and insulin resistance." (PMID 40648980, 2025). "This is supported by recent research demonstrating that cGAS‐STING can amplify NLRP3 activation in response to cytosolic DNA accumulation in conditions like intervertebral disc degeneration, acute liver injury, and insulin resistance." (PMID 40522023, 2025). "Compound C significantly reduces insulin resistance in HFD-induced obese mice by downregulating components of NLRP3 inflammasome and pro-inflammatory markers." (PMID 40433411, 2025). "extract reduced weight gain, hepatic lipid deposition, and improved dyslipidemia, inflammation, oxidative stress, and insulin resistance in HFD-fed mice via the regulation of the NF-κB/iNOS/COX-2/NLRP3/MAPK pathway." (PMID 40943363, 2025). "Activation of the NLRP3 inflammasome induces the production of pro-inflammatory cytokines and further promotes insulin resistance in patients with DN." (PMID 41357229, 2025). "LCN2 activates the NLRP3 axis, sustaining adipose inflammation, impairing mitochondrial glucose handling, and contributing to insulin resistance." (PMID 41303567, 2025). "RC also promotes the activation of NLRP3 inflammasome, thereby exacerbating insulin resistance-related inflammation through the upregulation of IL-1β." (PMID 41367915, 2025). "UA has been reported to activate the NLRP3 inflammasome and regulate hepatic steatosis and insulin resistance in an NLRP3 inflammasome-dependent manner." (PMID 40398602, 2025). "Despite the previous belief that uric acid was not a significant contributor to metabolic problems, uric acid directly induces hepatic steatosis and insulin resistance through NLRP3 activation." (PMID 40725208, 2025). "Previous studies have shown that HUA can activate the NLRP3 inflammasome pathway, promoting hepatic lipid accumulation and insulin resistance." (PMID 41391771, 2025). "Methyltransferase-like (METTL) 14-mediated m6A modification promoted NLRP3 inflammasome activation during arsenic-induced hepatic insulin resistance." (PMID 40307577, 2025). "We previously reported that UA regulates insulin resistance through an NLRP3 inflammasome-dependent mechanism and promotes the progression of NAFLD." (PMID 40398602, 2025). "This occurs through its impact on immune cell function, activation of the NLRP3 inflammasome, and induction of insulin resistance." (PMID 41301787, 2025). "n-3 PUFA supplementation in high-fat diet (HFD) mice has thus been demonstrated to prevent NLRP3 inflammasome-dependent insulin resistance in vivo." (PMID 40219010, 2025). "Mechanistically, insulin resistance facilitates the accumulation of free fatty acids, which activates the NLRP3 inflammasome and triggers a systemic inflammatory cascade." (PMID 41229520, 2025). "CIH promotes learning and memory impairment and insulin resistance through increased ROS production, which triggers the activation of NF-κB and subsequently activates the NLRP3 inflammasome in microglial cells." (PMID 39061946, 2024). "Omega-3 PUFAs also influence glucose metabolism potentially through modulation of the NLRP3 inflammasome, mitigating ROS production and mitochondrial impairment, thereby regulating insulin resistance progression via Ca2+ fluxes and ER stress." (PMID 39057711, 2024). "Mesenchymal stem cell was found to alleviate insulin resistance in T2DM rats by suppressing NLRP3 inflammasome-mediated inflammation and expression of IL-1β and IL-18." (PMID 38987672, 2024). "In experimental models, mice on a high-fat diet develop DMII, but deletion of the NLRP3 gene protects against insulin resistance, pancreatic islet fibrosis, and β-cell death." (PMID 39301197, 2024).
Insulin resistance (continued). "Inhibition of NLRP3 inflammasome-mediated myocardial ischemia-reperfusion injury.Insulin resistance downregulated by enhancing M2 macrophage polarization.Mediation of anti-tumor immunity in AML." (PMID 39650660, 2024). "Altogether, Zbtb18 transcriptionally activates the FXR-mediated FAO and CLTC expression, which inhibits NLRP3 inflammasome’s activity alleviating inflammatory stress and insulin resistance, representing an attractive remedy for hepatic steatosis and fibrosis." (PMID 38263084, 2024). "The literature suggests that the activation of inflammatory pathways, such as the NLRP3 inflammasome, and the release of proinflammatory cytokines contribute to insulin resistance and the development of T2D." (PMID 38919261, 2024). "Active adipocyte NLRP3 inflammasome contributes to mitochondrial dysfunction and insulin resistance." (PMID 37876013, 2023). "All the results showed that inhibiting NLRP3 inflammasome activation can restore the IR-IRS-AKT-AS160 insulin signaling pathway to alleviate insulin resistance in the 3×Tg-AD mice." (PMID 36978970, 2023). "Henriksbo and colleagues demonstrated that mice treated with statins exhibited insulin resistance in adipose tissue with concomitant activation of the NLRP3/caspase-1 axis." (PMID 37336361, 2023). "Activation of NLRP3 inflammasome was shown to contribute to As-induced hepatic insulin resistance by suppression of glycolysis via binding to pyruvate kinase, liver and RBC (PKLR)." (PMID 37624175, 2023). "The significance of a cytosolic oligomer complex called the NLRP3 inflammasome has been recognized in the progression of insulin resistance and in the development of T2DM." (PMID 37238986, 2023). "The insulin resistance, liver injury and NLRP3 inflammasome activity were higher in pre-diabetic individuals than in normal control group." (PMID 36817440, 2023). "The nucleotide-binding domain and the leucine-rich, repeat-containing family, pyrin-containing 3 (NLRP3) inflammasome, mediate obesity-induced inflammation and insulin resistance." (PMID 36779088, 2023). "By inhibiting NLRP3 inflammasome, apelin ameliorates insulin resistance and promotes survival after severe burn in rats." (PMID 36779088, 2023). "Aside from the more common pro-inflammatory cytokines, the (NOD-like) pyrin domain containing 3 (NLRP3) inflammasome has gained popularity for its implications in insulin resistance." (PMID 37047241, 2023). "In this study, EGCG significantly improved glucose intolerance in HFD-fed mice exposed to PFDA, suggesting the important role of NLRP3 inhibition in the amelioration of insulin resistance in mice co-exposed to an HFD and PFDA." (PMID 38067561, 2023). "They identified a mechanism of statin-induced reduction in prenylation isoprenoids leading to NLRP3 activation and insulin resistance." (PMID 37336361, 2023). "The active NLRP3 inflammasome also triggers insulin resistance via disturbance of AKT or the phosphatidylinositol 3-kinase/protein kinase B signaling pathway." (PMID 37238986, 2023). "Lysophosphatidylcholine can activate the NLRP-3 inflammasome in adipose tissue, contributing to the development of insulin resistance." (PMID 36768404, 2023). "Subsequent studies have indicated that statin-mediated activation of the NLRP3 inflammasome preceded insulin resistance and occurred via p38 and mTOR signaling." (PMID 37336361, 2023). "A recent experimental study showed that the glyburide exerts an effect on modulating depressive like-behaviour together with insulin resistance via an NLRP3-inflammasome inhibition." (PMID 36873988, 2023). "In line with our results, one latest research also showed that the blood glucose, insulin resistance, and NLRP3 inflammasome activity were higher in pre-diabetic patients than in normal control subjects." (PMID 36817440, 2023).
Insulin resistance (continued). "Our results demonstrated that HF diet-induced insulin resistance was ameliorated by endogenous n-3 PUFAs via inhibition of HF diet-induced NLRP3 inflammasome activation and IL-1β release in adipose tissue, especially in adipose tissue preadipocytes." (PMID 36234919, 2022). "The results showed that the CK treatment improved insulin resistance, alleviated cognitive dysfunctions, relieved oxidative stress, attenuated inflammatory responses in the hippocampus, and inhibited NLRP3 activation." (PMID 35276849, 2022). "A disturbance in UA has been reported to possibly be responsible for an impairment in lipid metabolism and insulin resistance through the NLRP3 inflammasome." (PMID 36556179, 2022). "Irisin can inhibit the formation and activation of NLRP3 inflammasome, thereby improving insulin resistance." (PMID 36248820, 2022). "It was also found that the arsenite methyltransferase (AS3MT) interacts with and activates the NLRP3 inflammasome during arsenic-induced hepatic insulin resistance." (PMID 36233132, 2022). "• Polarization of macrophages into an M2 profile through the IL-13Rα1/IL-4R receptor. • Decrease insulin resistance. • Involved in increasing inflammation via the NLRP3 inflammasome. • Increases fatty acid oxidation in muscle." (PMID 35422689, 2022). "Curcumin also ameliorated MSU-induced peritoneal inflammation and HFD-induced insulin resistance through inhibiting NLRP3 inflammasome activation in mice models." (PMID 36741414, 2022). "It was determined that arsenic-induced NOD-like receptor protein 3 (NLRP3) inflammasome activation contributed to hepatic insulin resistance." (PMID 36233132, 2022). "SIRT2 is also able to prevent inflammaging development and insulin resistance by deacetylating NLR family pyrin domain containing 3 (NLRP3) in macrophages." (PMID 35328633, 2022). "The pathogenesis of diabetic cardiomyopathy is complex, which is related to glucose and lipid metabolism disorders, insulin resistance, oxidative stress damage, and activation of NLRP3 and a variety of inflammatory pathways." (PMID 35401934, 2022). "One study showed that Uric acid regulates hepatic steatosis and insulin resistance through the NLRP3 inflammasome." (PMID 35813625, 2022). "Upon activation of NLRP3, a large amount of proinflammatory cytokines including IL-1β and IL-18 are secreted, aggravating glucose intolerance and insulin resistance." (PMID 34948026, 2021). "In animal models, elimination of NLRP3 inflammasome protects from high-fat induced insulin resistance, while in obese diabetic individuals, adipose tissue expression of NLRP3 inversely correlates with the increase in insulin sensitivity after weight loss." (PMID 34966295, 2021). "With regard to T2DM, increasing evidence has indicated the association between chronic low-grade inflammation and T2DM, especially highlighting the essential role that the NLRP3 inflammasome plays in the development of obesity, insulin resistance and T2DM." (PMID 34948026, 2021). "The adipose Nod-like receptor protein 3 (NLRP3) inflammasome initiates insulin resistance; however, the mechanism of inflammasome activation in adipose tissue remains elusive." (PMID 33643070, 2021). "In this study, homocysteine (Hcy) was found to participate in insulin resistance via a NLRP3 inflammasome-related process." (PMID 33643070, 2021). "Given the apparent synergistic adverse effects of neurodegeneration and insulin resistance, it is important to determine how these conditions are related and to explore potential therapies such as blocking the NLRP3 inflammasome." (PMID 34769018, 2021). "We found that increased plasma levels of Hcy promotes insulin resistance by activating adipocyte and adipose tissue macrophage Nod-like receptor protein 3 inflammasomes (NLRP3)." (PMID 33643070, 2021). "After activation of the NLRP3 inflammasome, IL-1β is released to promote insulin resistance and induce β-cell functional impairment and apoptosis of the inflammasome." (PMID 33854691, 2021).
Insulin resistance (continued). "IL-1β activated by NLRP3 inflammasome can worse insulin resistance in human adipocytes, moreover, inhibition of IL-1β can reduce hyperglycemia in obese/diabetic rats." (PMID 33796528, 2021). "In this narrative review, the current understanding of NLRP3 inflammasome activation and regulation is highlighted, including its putative roles in adipose tissue dysfunction and insulin resistance." (PMID 33435142, 2021). "NLRP3 inflammasome activation seems to be a key regulator of adipocyte differentiation and drives adipocytes towards more insulin resistance." (PMID 33546399, 2021). "The inflammatory cytokines, such as interleukin-1β (IL-1β) which is primarily driven by NF-κB and/or NLRP3 inflammasome activation, were related to islet inflammation and insulin secretion as well as the development of insulin resistance." (PMID 35111067, 2021). "The NLRP3 inflammasome is also involved in Hcy-induced adipose insulin resistance; Hcy acted as a second signal activator of the adipocyte NLRP3 inflammasome, and the adipocyte inflammation participates in lipid disorders and insulin resistance." (PMID 33643070, 2021). "BRB also inhibited obesity-induced ATMs infiltration and NLRP3 inflammasome activation in adipose tissue, subsequently suppressing insulin resistance in a mice model fed with a high-fat diet." (PMID 34684819, 2021). "Taken together, our data revealed the protective role of Nlrp3 deletion in the regulation of fear memory and the development of Aβ-insulin resistance, providing a novel target for the clinical treatment of this disorder." (PMID 34769018, 2021). "In our recent study, we found that SAL improves insulin resistance in high-glucose-incubated hepatocytes through AMP-activated protein kinase- (AMPK-) mediated inhibition of the NLRP3 inflammasome." (PMID 34457117, 2021). "We also tested the effect of MCC950, a highly specific inhibitor of NLRP3, on insulin resistance in the skeletal muscle." (PMID 34638553, 2021). "Hcy-induced activation of NLRP3 inflammasomes were observed in adipose tissue during the generation of insulin resistance in vivo." (PMID 33643070, 2021). "Based on these results, we suggest that both NLRP3 inflammasome priming and assembly steps are activated in skeletal muscle during insulin resistance." (PMID 34638553, 2021). "Disruption of phosphatidylinositol 3-kinase-protein kinase B (PI3K-Akt) signaling plays a major role in NLRP3-mediated insulin resistance." (PMID 33435142, 2021). "The NLRP3 inflammasome is activated by HHcy treatment and promotes insulin resistance and adipose inflammation." (PMID 33643070, 2021). "This study was devoted to the understanding of the potential therapeutic roles of the NLRP3 inflammasome in neurodegeneration occurring concomitant with brain insulin resistance and its contribution to the progression of emotional disorders." (PMID 34769018, 2021). "The production of inflammatory cytokines through activation of TLR and NLRP3 contributes to the development of insulin resistance by suppressing insulin signaling." (PMID 33519369, 2020). "The activation of NLRP3 inflammasomes to produce IL-1β leads to the coexistence of depressive-like behavior and insulin resistance in CUMS mice." (PMID 32166013, 2020). "SIRT2 mediated deacetylation of NLRP3 inhibits aging and HFD associated inflammation and insulin resistance in vivo." (PMID 32883606, 2020). "All of these findings were demonstrated by generating APOE2/NLRP3 KI mice which, similar to arglabin treatment, showed a reduction in plasma glucose and insulin resistance in mice on a HFD." (PMID 32650482, 2020). "The biochemical changes that occur as a consequence of excess nutritition, insulin resistance and aging have been shown to mediate NLRP3 priming via various mechanisms." (PMID 32883606, 2020). "Since the activation of the NLRP3 inflammasome has a critical function in insulin resistance, we analyzed the level of inflammasome relative proteins in the pancreas of pregnant mice." (PMID 31558153, 2019).